HIF1A (hypoxia inducible factor 1 subunit alpha)
Diseases named in the same sentence as HIF1A in open-access papers (continued):
Sharing a sentence is not in itself a finding about the gene and the disease.
ovarian carcinoma (continued). "The present study, therefore, aims to investigate the potential role of the miRNAs miR-138, -210 and -335 and their downstream effector, HIF-1α and MMP9, as well as changes induced by sevoflurane or desflurane, which are commonly used clinically on ovarian cancer cell biology and malignancy." (PMID 33673181, 2021). "Resveratrol substantially induced HIF-1α protein degradation through the proteasome pathway and also greatly inhibited VEGF expression and thus provided a novel potential mechanism for inhibiting human ovarian cancer progression." (PMID 34829589, 2021). "We also noted that the induction of BCL2A1 expression coincided with the induction of HIF-1α at 2 h after hypoxia treatment, indicating that BCL2A1 may be an early response factor of hypoxia in ovarian cancer cells." (PMID 34572804, 2021). "At the range of physiologically relevant concentrations, IGF-1 markedly induced HIF-1α and NOX4 expression levels in human ovarian cancer A2780 and OVCAR3 cells, thus HIF-1α might be one of the mechanisms regulating the expression level of NOX4." (PMID 34209278, 2021). "As a final conclusion, the authors summarized that HIF1α and SIRT1 might serve as potential therapeutic targets for ovarian cancer, establishing an interesting connection between different pathways of observed disturbances and cancer pathogenesis." (PMID 33435147, 2021). "In ovarian cancer models, LPA induces a shift towards glycolysis, upregulates hexokinase 2, and induces metabolic reprograming via a pseudo-hypoxic response that is HIF1α-mediated." (PMID 33671212, 2021). "SIRT1 was overexpressed in ovarian cancer cell exposure to hypoxia condition, and the NF-κB signaling pathway was involved in hypoxia-induced SIRT1 up-regulation—HIF-1α promoted CSCs-like features by increasing SIRT1 expression via NF-κB signaling pathway activation." (PMID 33435147, 2021). "Moreover, HIF-1α knockdown also greatly increased radiation sensitivity, indicating that HIF-1α was an effector of NOX4 for mediating radiation resistance in ovarian cancer cells." (PMID 34209278, 2021). "In contrast, in the present study, β-escin did not affect HIF1α production in ovarian cancer cells, but did regulate HIF1α stability." (PMID 34439084, 2021). "Additionally, estrogen and progestin can directly regulate HIF-1α through the PI3K/Akt-mTOR signaling pathway and contribute to tumor metastasis in ovarian cancer." (PMID 34867818, 2021). "On the other hand, GHET1 may stabilize the HIF-1α protein and prevent it from degradation by VHL as demonstrated in in vitro experiments in ovarian cancer cell lines." (PMID 32640630, 2020). "Although HIF-1α is the major transcriptional factor for several genes under hypoxic conditions, GM-CSF in ovarian cancer cell was not upregulated after treatment with CoCl2, which mimics hypoxia-stabilising HIF-1α protein." (PMID 31932754, 2020). "However, activation of HIF-1α and VEGF signaling pathways and subsequent migration of the ovarian cancer cells by LPA were attenuated by resveratrol." (PMID 30791624, 2019). "In ovarian cancer cells, increased TSG101 levels upregulate CBP/p300-interacting transactivator with ED-rich tail 2 (CITED2) and hypoxia-inducible factor 1α (HIF-1α), while downregulating tumor suppressor p21 and subsequently promoting cell growth and survival." (PMID 30759747, 2019). "Furthermore, we report that MSA decreases the levels of PDL1, HIF-1α, and VEGF in ovarian cancer cell lines and thereby renders the tumor cell sensitive to T cells, turning MSA into an interesting candidate for combinational treatments." (PMID 30324091, 2018). "Mechanistically, CT exerted its anti‐tumor effect by targeting STAT3/SIRT3/HIF‐1α signaling pathway in vitro and in vivo, which could be rescued by the introduction of SIRT3 shRNA in ovarian cancer cells." (PMID 30094960, 2018). "HIF-1α and VEGF levels were positively correlated with ovarian cancer metastasis." (PMID 29770329, 2018).
ovarian carcinoma (continued). "In addition, AEG-1, HIF-1α, NF-κB, and VEGF mRNA and protein levels were determined by reverse quantified RT-PCR and WB, respectively, at different time periods (0–24 h) in epithelial ovarian cancer (EOC) SKOV3 cells treated in a hypoxia incubator." (PMID 29770329, 2018). "HIF‐1α binds to AEG‐1 promoter and induces upregulated AEG‐1 expression to enhance metastasis in ovarian cancer by increasing MMP2 and MMP9 expression as well as attenuating E‐cadherin and β‐catenin expression during hypoxia, which is a typical feature of tumor microenvironment." (PMID 28401704, 2017). "Our results indicate that TS may selectivity inhibit human ovarian cancer cells by mediating apoptosis through the extrinsic pathway, and initiating anti-angiogenesis via decreased VEGF protein levels in a HIF-1α-dependent pathway." (PMID 28974006, 2017). "In this experiment, AEG‐1 induction in ovarian cancer likely occurs through coordinated control by hypoxia‐regulated gene expression, and as previously reported, AEG‐1 was recently shown to induce HIF‐1α as well as Tie2 and VEGF 23, which forms a positive feedback loop." (PMID 28401704, 2017). "The data showed that knockdown of HIF-1α expression cloud significantly reduced the expression of CSCs’ markers, chemoresistance, tumorigenesis and EMT phenotype in ovarian cancer cells." (PMID 28878214, 2017). "Our results hinted that HIF1α and SIRT1 might serve as potential therapeutic targets for ovarian cancer." (PMID 28878214, 2017). "Our results showed that EnSCs impaired the pro-angiogenetic ability of ovarian cancer cells in vivo through decreasing the expressions of VEGFA and HIF-1α in EOC cells, which might be mediated by EnSC-induced activation of FoxO3a in cancer cells." (PMID 27845405, 2016). "Directly targets HIF-1α, reversing HIF-1α-mediated induction of ovarian cancer cell invasion." (PMID 27551267, 2016). "The silencing of HIF1α in the cells inhibited the increased expression of N-cadherin and Slug along with the decreased expression of E-cadherin, thus validating the conclusion that HIF1α in LPA-induced EMT of ovarian cancer cells is dependent on HIF1α." (PMID 27166196, 2016). "In this context, our present observation that the clinically relevant dose of PX-478 (25 μM) potently inhibits the invasive migration of ovarian cancer cells further establishes the therapeutic potential of the LPA-Gai-HIF1α signaling node, especially in HIF1α overexpressing ovarian cancers." (PMID 27166196, 2016). "Thus, our present study demonstrates that LPA utilizes a Gαi2-mediated signaling pathway via Src kinase to stimulate an increase in HIF1α levels and downstream EMT-specific factors such as Slug, leading to invasive migration of ovarian cancer cells." (PMID 27166196, 2016). "Thus, our current study demonstrates that LPA stimulates a signaling nexus involving Gαi2, Src, and HIF1α to induce EMT and migration of ovarian cancer cells." (PMID 27166196, 2016). "However, under these conditions, they express higher levels of HIF-1α as compared to HIF-2α, and consistent with these findings, the levels of HIF-1α are higher in TAMs infiltrating breast and ovarian carcinomas." (PMID 25072019, 2014). "Similarly, miR-125b and miR-199a were also shown to act as tumor suppressors by targeting HIF-1α and VEGF in ovarian cancer cells, consequently reducing angiogenesis." (PMID 25295252, 2014). "Collectively, our study demonstrates that the hypoxia-HIF-1α, LOX-FAK/AKT pathway regulates the migration and invasion of epithelial ovarian cancer cells under hypoxia/reoxygenation conditions, thus, promoting metastasis of ovarian cancer." (PMID 23545606, 2013). "The few publications addressing the prognostic significance of Hypoxia-Inducible Factor 1α (HIF-1α) cellular expression in ovarian cancer produced contradictory findings which are not permissible to widely acceptable conclusions and clinical applications." (PMID 19014607, 2008).
ovarian carcinoma (continued). "The frequency of the nuclear expression of HIF-1α in benign tumours was significantly lower (median: no expression) than in borderline and ovarian cancer tumours combined (p < 0.001)." (PMID 19014607, 2008). "The frequency of the nuclear expression of HIF-1α in benign tumours differed significantly (median: no expression) than in borderline and ovarian cancer tumours combined (p < 0.001)." (PMID 19014607, 2008). "Integrative bioinformatics of cisplatin-treated ovarian cancer datasets from the Gene Expression Omnibus (n=255) identified six molecular drivers of resistance: Kaiso (ZBTB33), pregnane X receptor (PXR), NF-κB, HER2 (ERBB2), P-glycoprotein (P-gp/ABCB1), and HIF1A." (PMID 41438580, 2026). "Rg3 stops colorectal cancer cells from growing by blocking the Wnt/β-catenin pathway, helps ovarian cancer cells die by blocking the PI3K/AKT pathway, stops esophageal cancer cells from making new blood vessels when oxygen levels drop, and stops EMT in ovarian cancer by decreasing HIF-1α." (PMID 41321380, 2025). "In addition, the current study demonstrated that SHMT2 alternative promoter usage mediated by HIF1α and TFE3 might represent adaptive response of ovarian cancer cells to metabolic stress." (PMID 40097394, 2025). "Besides the upstream signaling of HIF-1α, the downstream effectors of HIF-1α might also be involved in the ovarian cancer malignancy, namely, C-X-C motif chemokine ligand 12 (CXCL12) and C-X-C motif chemokine receptor 4 (CXCR4)." (PMID 36207479, 2023). "This review focuses on ovarian cancer and the significance of key rate-limiting enzymes (hexokinase, phosphofructokinase, and pyruvate kinase, related signaling pathways (PI3K-AKT, Wnt, MAPK, AMPK), transcription regulators (HIF-1a), and non-coding RNA in the glycolytic pathway." (PMID 38090580, 2023). "Thus, HIF-1α over-expression significantly mitigated or abrogated the TRMP7 silencing-decreased glycolysis and inhibition of AMPK abrogated the TRPM7 silencing-enhanced OXPHOS in ovarian cancer cells." (PMID 35101076, 2022). "In ovarian carcinoma, elevated expression of HIF1A alone is not considered a prognostic marker." (PMID 36230822, 2022). "Treatment with MG132, a proteasome inhibitor, remarkably restored HIF-1α protein levels in ovarian cancer cells regardless of hypoxia condition and TRPM7 silencing, indicating that TRPM7 silencing promoted the ubiquitination and proteasomal degradation of HIF-1α." (PMID 35101076, 2022). "Indeed, HIF-1α had no obvious effect on BCL2A1 expression in ovarian cancer cells under hypoxic conditions, suggesting that BCL2A1 induction by hypoxia occurs in a HIF-1α-independent manner." (PMID 34572804, 2021). "Furthermore, using CRISPR/Cas9-mediated HIF-1α gene knockout and co-treatment of CoCl2-simulated hypoxia in ovarian cancer cells, OVCA433 and ES-2, the changes of HIF-1α also did not alter the protein expression level of BCL2A1." (PMID 34572804, 2021). "Therefore, PI3K, Akt, HIF-1α, Twist1, and DDR2 may serve as effective targets to attenuate the invasion and metastasis of ovarian cancer cells." (PMID 34065317, 2021). "Additionally, overexpression of AEG-1 and HIF-1α were significantly higher in patients with stage III or IV ovarian carcinoma, as opposed to stage I or II (p < 0.001 for both)." (PMID 33671513, 2021). "In addition, NE could induce expression of human telomerase reverse transcriptase (hTERT) to promote ovarian cancer cell EMT and invasion by regulating ADBR2/PAK/Src/HIF-1α and c-Myc signaling pathway." (PMID 32934214, 2020). "The effect of HVEM- HIF-1α axis in ovarian cancer is not fully elaborated." (PMID 32312328, 2020).
ovarian carcinoma (continued). "In human colon and ovarian cancer cells, under non-hypoxic conditions, prolyl-1-4 hydroxylase proteins (PHDs) hydroxylate HIF-1α, which then binds von-Hippel-Lindau proteins, causing proteasomal degradation of HIF-1α." (PMID 31681793, 2019). "For example, in ovarian carcinoma cell lines, SRg3 was the only epimer that inhibited migration and invasion via blocking hypoxia-induced epithelial-mesenchymal transition (EMT), the degradation of hypoxia-inducible factor-1α (HIF-1α) and the transcriptional repression of Snail and hence E-cadherin." (PMID 31374984, 2019). "In addition, AEG-1 could regulate hypoxia induced transcription of HIF-1α, NF-κB, and VEGF in ovarian cancer cells." (PMID 29770329, 2018). "Our data suggested that HIF-1α and SIRT1 could be predictors for chemoresistance and prognosis of ovarian cancer and they will be the targets for the development of new therapies for ovarian cancer." (PMID 28878214, 2017). "Rg3 inhibits the proliferation of colorectal cancer by inhibiting the Wnt/Δ-catenin pathway, promotes apoptosis of ovarian cancer cells by inhibiting the PI3K/AKT pathway, inhibits angiogenesis of esophageal cancer induced by oxygen deficit, and inhibits EMT in ovarian cancer by reducing HIF-1α." (PMID 26636541, 2016). "Therefore, we set out to determine if LPA signaling could enhance the levels of HIF1α and subsequent EMT of ovarian cancer cells in a hypoxic environment." (PMID 27166196, 2016). "To determine whether LOX and HIF-1α expression increases in ovarian cancer tissues, we examined the expression of LOX and HIF-1α in 44 cases of human epithelial ovarian carcinoma, 20 cases of borderline ovarian tumor, 27 cases of benign ovarian tumor and 28 cases of normal ovarian tissues." (PMID 23545606, 2013). "Serous ovarian cancer cell lines OVCA420 and OVCA429 were growth inhibited in hypoxia (1% O2) and glucose deprivation (HG) conditions and the transfection with siRNA targeting HIF1 α and ENO1 has limited effect on further growth inhibition compared to the control transfected cells." (PMID 21754983, 2011). "This combination, with or without cisplatin, successfully offset the increased HIF-1α and CSC population seen in bevacizumab monotherapy and suppressed the growth of ovarian cancer." (PMID 37460927, 2023). "On the other hand, in ovarian cancer tissue samples, VEGFA was correlated neither with HIF1A nor EPAS1, but HIF1A was positively and moderately correlated with EPAS1 (R = 0.57, p < 0.0001)." (PMID 36230822, 2022). "HIF1α expression did not correlate with either VEGFA/B or MVD, as previously reported for a small cohort (n = 60) of ovarian cancer cases." (PMID 34680301, 2021). "Our findings showed that NF-ĸB p65 (RELA) but not HIF-1α had four putative binding sites on the promoter of BCL2A1, indicating that NF-κB signaling was the upstream inducer of BCL2A1 in ovarian cancer cells." (PMID 34572804, 2021). "Even more, Xia and collaborators demonstrates that H2O2 treatment of ovarian cancer cells OVCAR-3 greatly increased HIF-1α expression up to 6h, whereas the HIF-1α-1β level was not changed." (PMID 32183322, 2020). "Furthermore, LPA through stabilization of HIF-1a (a master regulator of the glycolysis in tumors) may alter cellular metabolism of HCV or HBV-infected Heps towards glycolysis, a key metabolic pathway that fuels cancer and stromal cells as shown in ovarian cancer." (PMID 31652837, 2019). "Furthermore, in designing a HIF-1α-targeting clinical trial, it would be important to optimize the assessment of HIF-1α expression by using a panel of antibodies to accurately identify subgroups of ovarian carcinoma patients who could benefit from novel HIF-1α-inhibiting therapeutic strategies." (PMID 19014607, 2008). "Interestingly, prior studies have also shown that 4-OHE2, but not 2-OHE2, can increase Hif1a and Vegf via the PI3K/AKT/FRAP pathway in ovarian cancer cells (OVCAR-3)." (PMID 40869324, 2025).
ovarian carcinoma (continued). "HIF-1α also targets and upregulates the stanniocalcin (STC) gene, known for being an anti-hypercalcemic glycoprotein hormone, although not much research has been focused on STC in ovarian cancer tumorigenesis." (PMID 34867818, 2021). "In another study using ovarian cancer cells treated with cisplatin under hypoxia, the authors also highlighted the role of STAT3 in this context, however whether HIF-1α is important was not examined." (PMID 29036915, 2017). "However, the precise linkage between metabolism dysfunction (HIF-1α, AMPK) and the propensity for tumourigenesis has not been fully elucidated in ovarian carcinoma." (PMID 25491408, 2014). "It is encouraging that ABZs significantly inhibited the expression of HIF-1α in non-small cell lung cancer and ovarian cancer; however, ABZ treatment did not affect the HIF-1α mRNA level, suggesting that other unknown regulatory pathways may be involved in this process." (PMID 33996598, 2021).